PGPEP1L (pyroglutamyl-peptidase I like)
Tractability: No criterion of Open Targets' tractability assessment is met for any kind of drug.
Gene: Protein-coding gene on chromosome 15 (98,966,720 to 99,007,792, reverse strand). Ensembl gene ENSG00000183571.
Subcellular location (Human Protein Atlas): Equatorial segment; Cytosol; Plasma membrane
Gene Ontology:
Molecular function: peptidase activity
Genetic constraint (gnomAD): Loss-of-function variants: 7 observed, 6.3 expected, observed/expected ratio (o/e) 1.11, 90% interval 0.62 to 1.83. That is too few expected variants to judge how well the gene tolerates losing a copy. Missense variants: 195 observed, 183.62 expected, observed/expected ratio (o/e) 1.06, 90% interval 0.94 to 1.2. Synonymous variants: 98 observed, 82.34 expected, observed/expected ratio (o/e) 1.19, 90% interval 1.01 to 1.41.
Homologues: Orthologues: chimpanzee PGPEP1L (89% identical), macaque PGPEP1L (77% identical), mouse Pgpep1l (65% identical), dog PGPEP1L (62% identical), rat Pgpep1l (61% identical), tropical clawed frog pgpep1l (46% identical), zebrafish pgpep1l (39% identical), Caenorhabditis elegans M04C9.1 (23% identical), Caenorhabditis elegans M04C9.2 (22% identical), Caenorhabditis elegans M04C9.3 (22% identical), Drosophila melanogaster CG32147 (20% identical), Caenorhabditis elegans W04E12.7 (19% identical), and 4 more. Paralogues in human: PGPEP1 (40% identical).